RN7SL199P (RNA, 7SL, cytoplasmic 199, pseudogene)
Gene: Miscellaneous RNA gene on chromosome 17 (46,537,534 to 46,537,814, forward strand). Ensembl gene ENSG00000265315.
Homologues: Orthologues: chimpanzee Metazoa_SRP (95% identical), macaque Metazoa_SRP (93% identical), macaque Metazoa_SRP (92% identical), chimpanzee Metazoa_SRP (89% identical), rabbit Metazoa_SRP (68% identical). Paralogues in human: RN7SL656P (100% identical), Metazoa_SRP (99% identical), RN7SL270P (99% identical), RN7SL404P (96% identical), RN7SL1 (85% identical), RN7SL3 (85% identical), RN7SL2 (84% identical), RN7SL45P (82% identical), RN7SL333P (81% identical), RN7SL712P (81% identical), RN7SL804P (81% identical), RN7SL88P (81% identical), and 707 more.